MMP2 (matrix metallopeptidase 2)
Diseases named in the same sentence as MMP2 in open-access papers (continued):
Sharing a sentence is not in itself a finding about the gene and the disease.
metabolic syndrome (24 papers, 2011 to 2024). A cluster of metabolic risk factors for CARDIOVASCULAR DISEASES and TYPE 2 DIABETES MELLITUS. "Elevated levels of MMP2 are linked to a chronic low-grade inflammation present in cardiometabolic diseases, all of which are also associated with dyslipidemia." (PMID 37434164, 2023). "While MMP2 has been reported to be increased in metabolic syndrome and cardiovascular disease, its deficiency has also been reported to be associated with metabolic and inflammatory pathologies, pointing toward a complex relationship of MMP2 with cardiometabolic disorders." (PMID 34016094, 2021). "Experimental and clinical studies have reported that the synthesis and activities of MMP-2 and -9 are altered during metabolic syndrome or according to variations in diet types ingested." (PMID 36902320, 2023). "It is known that MMP-2 plasma concentration can be increased in patients with isolated systolic hypertension and in patients with metabolic syndrome." (PMID 35769087, 2022). "The MMPs, particularly MMP-2 and MMP-9, are elevated in patients with morbid obesity, metabolic syndrome, and T2DM." (PMID 39766340, 2024). "In the group of patients with dyslipidemia and the confirmed presence of unstable atherosclerotic plaque, plasma levels of OPG, OPN, MMP-2, and MMP-9 are significantly higher compared to the group of healthy people." (PMID 35743980, 2022). "MMP-1 seems to be involved in the development of adipose tissue, while plasma levels of MMP-2 and MMP-9 are elevated in patients with the metabolic syndrome." (PMID 34512552, 2021). "Studies in humans have shown that the plasma levels of MMP-2 and MMP-9 are elevated in patients with the metabolic syndrome." (PMID 34512552, 2021). "Studies suggest that specific MMPs, such as MMP-2 and MMP-9, play a fundamental role in cardiac remodeling and degradation of the extracellular matrix in individuals with dyslipidemia." (PMID 32881885, 2020). "Levels of MMP2, MMP9, TIMP-1 and TIMP-2 are all increased in diabetic patients with dyslipidemia or with acute coronary syndrome." (PMID 25204377, 2014). "The combined treatment is also able to improve dyslipidemia, and to decrease TNF-α, TGF-β, collagen-I and collagen-III and increased MMP-2 but within a greater effect than treatment with rosiglitazone alone." (PMID 21450068, 2011). "Plasma concentrations of MMP-2 and MMP-9 are increased in patients with metabolic syndrome." (PMID 35769087, 2022). "Several studies demonstrated that plasma MMP-2 levels or MMP-2 gene expression in visceral adipose tissue were not modified in obese or metabolic syndrome people." (PMID 34625635, 2021). "Since the concentrations of MMP-2 and MMP-9 are higher in patients with the metabolic syndrome and TIMP-1 is significantly higher in obese patients, we assumed that the higher concentrations of the analyzed markers are the consequence rather than the cause of cardiometabolic complications." (PMID 30245717, 2018). "The plasma levels of MMP-2 and MMP-9 are elevated in patients with metabolic syndrome, with or without diabetes mellitus." (PMID 30245717, 2018). "The aim of this study is to investigate the plasma levels of MMP-1, MMP-2, MMP-3, MMP-9, TIMP-1, TIMP-2 and their ratios in a large variety of study groups including overweight people and obese people with or without metabolic syndrome and non-obese healthy people with total of 479 participants." (PMID 34625635, 2021).
leukemia (23 papers, 2003 to 2025). A malignant (clonal) hematologic disorder, involving hematopoietic stem cells and characterized by the presence of primitive or atypical myeloid or lymphoid cells in the bone marrow and the blood. "Altogether, these presented results confirm that HU targeting insufficient MMP2 played a causal role in evoking HU susceptibility of MLL-r leukemia cells." (PMID 35396375, 2022). "Members of the matrix metalloproteinase family have been implicated in the migration and invasion of leukemia cell (MMP-2), and previously shown to mediate megakaryocyte transendothelial migration and proplatelet formation (MMP-9)." (PMID 29420626, 2018). "Researchers from Taiwan concluded that although MMP-2 promoter genotypes play a minor role in the assessment of the risk of developing leukemia, the MMP-7 A-181G genotype may serve as a predictive biomarker for childhood ALL." (PMID 32751899, 2020). "Other studies have focused on the connection between MMP-2 and MMP-7 genotypes and the risk of childhood leukemia." (PMID 39996769, 2025). "In macrophages, eNAMPT promotes cell survival upon ER stress, up-regulates MMP-9 and MMP-2, and is able to induce the M2-polarization of macrophages in leukemia." (PMID 36674688, 2023). "Subsequently, we ought to unravel why these HU-sensitive MLL-r leukemia cell lines have reduced the expression of MMP2." (PMID 35396375, 2022). "On the contrary, in some cancers such as in leukemia, MMP-2 and MMP-9 bind to CD44 in a complex where MMP-14, interacting with CD44v6, cleaves and activates MMP-2, inducing the degradation of the extracellular matrix." (PMID 33505471, 2021). "Most recent studies have focused on the connection between MMP-2 and MMP-7 genotypes and the risk of childhood leukemia." (PMID 32751899, 2020). "Excessive secretion of MMP2 by leukemia cells would increase the permeability of the blood-brain barrier via disrupting the tight junction proteins, leading to enhance the invasion of leukemia cells into the central nervous system." (PMID 36569343, 2022). "MMP-2 and MMP-9 have been associated with degradation of endothelial tight junction proteins, permeabilization of the blood-brain-barrier (BBB) and subsequent brain colonization in mouse models of leukemia." (PMID 25668816, 2015). "Total and pro-MMP-2 also contributed to the Cancer and Leukemia Group B prognostic groups." (PMID 12771921, 2003). "Altogether, we validated that MLL controls the transcription of the MMP2 gene, and decreased MLL in MLL-r leukemia cells accounts for insufficient MMP2 and HU sensitivity, and our rough exploration also suggests a possible role of MMP2 in UPR pathways." (PMID 35396375, 2022). "AMSA is known to suppress MMP-2 and MMP-9 expression in human leukemia cells via reactive oxygen species (ROS) generation." (PMID 31848363, 2019). "A previous study demonstrated that FN-mediated cell adhesion is required for the induction of MMP-2 and MMP-9 in human leukemia cells." (PMID 29706869, 2018). "PRO has also been shown to inhibit the expression of the tissue remodelling factor matrix metalloproteinase-2 (MMP-2) and the pro-angiogenic vascular endothelial growth factor (VEGF) in human leukaemia cell lines." (PMID 27899953, 2016). "In order to investigate the relationship between leukemic cell-derived MMP-2 and -9 and the BBB in CNS leukemia, we first studied the effect of MMP-2 and -9 secreted by different leukemic cells on cultured BMVECs in the in vitro model of the BBB." (PMID 21857898, 2011). "Except the well known role of degrading extracellular matrix in metastasis of cancer cells, here we show matrix metalloproteinase (MMP)-2 and -9, secreted by leukemic cells, mediate the BBB opening by disrupting tight junction proteins in the CNS leukemia." (PMID 21857898, 2011). "Collectively, these results demonstrate that the loss of endothelial TJ proteins ZO-1, claudin-5 and occludin leaded by MMP-2 and -9 is a central event in the opening of the BBB in CNS leukemia." (PMID 21857898, 2011).
leukemia (continued). "In vitro studies have described the role of MMP secretion (MMP-2 and MMP-9) by leukemia cells contributing to invasion capacity, most notably of the blood-brain barrier, with upstream regulation by mitogen-activated protein kinases (MAPKs) and phosphoinositide 3-kinase (PI3-K)/AKT pathways." (PMID 36900239, 2023). "Interestingly, low MMP2 level suggested a shorter life term in these patients, consistent with high malignancy of MLL-r leukemia." (PMID 35396375, 2022). "Besides, GLY also decreased the expression level of p-FAK, p-Akt, p-ERK, p-Rb, MMP-2, and MMP-9 whereas increased p21 expression to attenuate leukemia cell growth and migration." (PMID 23573143, 2013). "We have thus hypothesized that MMP-2 and -9 secreted by leukemic cells may play critical roles in the BBB opening in CNS leukemia by disrupting TJ proteins." (PMID 21857898, 2011). "Additionally, TIMP-2 (tissue inhibitor of metalloproteinase 2) upregulation has been seen with increased leukemia cell line (i.e., SHI-1) invasion both in vitro and in vivo with more extensive and severe extramedullary infiltration through both MMP-2-dependent and independent activities." (PMID 36900239, 2023). "Besides that, the expression of MMP-2 was also related to extramedullary infiltration in adult ALL, although the same was not verified for childhood leukemia." (PMID 40427122, 2025).
cholangiocarcinoma (22 papers, 2009 to 2025). A carcinoma that arises from the intrahepatic biliary tree (intrahepatic cholangiocarcinoma) or from the junction, or adjacent to the junction, of the right and left hepatic ducts (hilar cholangiocarcinoma). "To identify the mechanism underlying the effects of β6 on invasion in cholangiocarcinoma cells, we measured the mRNA expression of uPA, MMP2, MMP3, and MMP9 using quantitative real-time PCR after silencing or overexpressing β6." (PMID 27440504, 2016). "Moreover, we found that metastasis of cholangiocarcinoma is associated with the translocation of β-catenin and upregulation of cyclinD1, c-Myc and MMP2." (PMID 26474277, 2015). "Furthermore, we found that metastasis of cholangiocarcinoma is associated with the translocation of β-catenin and upregulation of cyclinD1, c-Myc and MMP2." (PMID 26474277, 2015). "Activation of cyclic AMP response element binding protein (CREB) has been reported to induce MMP2 expression in cholangiocarcinoma." (PMID 40779492, 2025). "Expression of miR-380 is abnormal in cholangiocarcinoma, and its upregulation reduces the expression of MMP-2/p-AKT through targeted regulation of LIS1, thereby inhibiting the proliferation, S-phase arrest and invasiveness of cholangiocarcinoma cells." (PMID 38582841, 2024). "An imbalance of miR-380 expression is closely related to cholangiocarcinoma, and overexpression of miR-380 inhibits the expression of MMP-2/p-AKT by directly targeting LIS1." (PMID 38582841, 2024). "The activities of MMP-2 and loss of balanced expressions of MMP-2/TIMP-2 and MMP-9/TIMP-1 are suggested as playing important roles in invasive growth related to the gross type of cholangiocarcinoma." (PMID 27933122, 2009). "In addition, we investigated on β-catenin and β-catenin-related molecules, including MMP-2, c-Myc, in human cholangiocarcinoma cell lines QBC939 and Mz-ChA-1 when treated with MSCs or MSC-CM." (PMID 26474277, 2015). "Human umbilical cord-derived MSCs co-cultured with a human cholangiocarcinoma cell line produced conditioned media that contributed to drug resistance and metastasis through increased Wnt activation and the upregulation of Wnt target genes (matrix metalloproteinase 2 (MMP2), cyclin D1, and c-myc)." (PMID 33105836, 2020). "MMP2 and MMP9 are key enzymes involved in extracellular matrix degradation, promoting tumor invasion, metastasis, and angiogenesis in cholangiocarcinoma." (PMID 41300430, 2025). "Collectively, MMP2 and MMP9 serve as both prognostic biomarkers and potential therapeutic targets in cholangiocarcinoma." (PMID 41300430, 2025). "In vitro experiments showed that miR-380 affected expression of MMP-2 and p-AKT by targeting LIS1, thus participating in the regulation of the biological behavior of cholangiocarcinoma cells." (PMID 38582841, 2024). "Chan-on (2015) reported that nitroxoline significantly suppresses the cell migration and decreases the expression of MMP-2 and MMP-9 in cholangiocarcinoma cells." (PMID 33046984, 2020). "Likewise, a series of experiments performed in this study suggest that Huaier alone or combined with 5-FU could inhibit the invasion and metastasis of cholangiocarcinoma cells and those involved in the down-regulation of N-cadherin, Vimentin, MMP-2 and MMP-9 expression." (PMID 31391034, 2019). "Treatment of cholangiocarcinoma CCA cells with MAG decreased malignancy and proliferation of the cells by downregulation of PCNA, Ki67, MMP-2, -7 and -9 protein expression and inhibition of the NF-κB signaling pathway." (PMID 30103472, 2018). "Our results showed that β6 induced the expression of MMP9 but not that of uPA, MMP2 or MMP3 in cholangiocarcinoma cells." (PMID 27440504, 2016).
periodontal disease (21 papers, 2009 to 2024). "Increased activity of the ECM remodeling proteins MMP2/MMP9 is often associated with periodontal disease, where this activity is coordinately regulated by gene expression and controlled enzymatic activity by a wide range of cytokines and growth factors." (PMID 37892119, 2023). "Studies have shown that berberine suppresses the activity of matrix metalloproteinases (MMP)-2 and pro-MMP-2 in human gingival fibroblasts that are stimulated by LPS derived from periodontal disease–causing bacteria." (PMID 32992711, 2020). "Proteolytic enzymes released by host cells are associated with tissue destruction in periodontal diseases, specifically MMP-2 and MMP-9 have been implicated in periodontal disease progression." (PMID 23843954, 2013). "Increased expression of MMP-2 and -8 in periodontal disease has already been reported by previous studies that analyzed gingival crevicular fluid, which also identified their diagnostic potential for periodontal disease." (PMID 35562715, 2022). "Although many studies have shown that several MMPs contribute to the progression of periodontal disease, such as MMP-2, -7, and -14, the most reported MMPs that are responsible for periodontopathy are collagenases MMP-1, -8, and -13." (PMID 35163727, 2022). "The mechanism of increased expressions of MMP-2 and -8 in periodontal disease is suspected to involve Porphyromonas gingivalis and IL-1." (PMID 35562715, 2022). "The study also identifies that actin dynamics play a role in the progression of periodontal disease, specifically actin depolymerization as a key contributor to enhance MMP-2 activity." (PMID 34094999, 2021). "Overall, our results showed selective inhibition of IL-1β, TNF-α, IL-8, MMP-2, and MMP-9 associated with hesperidin, which could represent a promising novel approach to the treatment or prevention of periodontal disease." (PMID 37373533, 2023). "Tissue destruction caused by MMP-2 and MMP-9 was reduced in animals treated with 5 mg/kg AZT, indicating that IL-10 may be a protective cytokine in periodontal diseases." (PMID 24819928, 2014). "The results of the present study confirm that MF suppresses MMP-1, MMP-2, MMP-8 and IL-8 in LPS-stimulated HGFs suggesting an anti-inflammatory effect of MF and potential adjunct therapeutic role in the treatment of periodontal diseases." (PMID 37189090, 2023). "Because type I collagen is the major component of the periodontal extracellular matrix, special attention has been paid to the role of collagenases, especially MMP-8 and MMP-13 and gelatinases, MMP-2 and MMP-9, in periodontal diseases." (PMID 35163727, 2022). "On the other hand, MMP-2 and MMP-9 are mainly synthesized by neutrophils and macrophages and are involved in MMPs-mediated destructive periodontal disease." (PMID 35163727, 2022). "Our study is innovative because it demonstrated a reduction in the formation of MMP-2 and MMP-9 in an experimental model of periodontal disease." (PMID 23843954, 2013). "Dysregulation of myocardial metalloproteinases (MMPs) is now regarded as an early contributing factor to the initiation and progression of heart failure and pre-treatment with Carvedilol prevented MMP-2 and MMP-9 expression shown to be activated in periodontal disease." (PMID 23843954, 2013).
sarcoma (21 papers, 2009 to 2025). A usually aggressive malignant neoplasm of the soft tissue or bone. "We demonstrated the complex formation and co-expression of CD73 and emmprin; further, we showed that CD73 was associated with the regulation of MMP-2 production in co-cultures of sarcoma cells with fibroblasts." (PMID 31510956, 2019). "Overexpression of MMPs, especially MMP-2 and -9 and low levels of TIMPs have been shown to be associated with a more aggressive behavior of sarcomas." (PMID 24190483, 2014). "Overproduction of MMPs, especially MMP-2 and -9 and low levels of TIMPs have been shown to be associated with a more aggressive behavior of sarcomas." (PMID 23661254, 2013). "Experiments using siRNA were performed to investigate whether CD99 and CD73 were associated with the regulation of MMP-2 production from co-cultures of sarcoma cells with fibroblasts." (PMID 31510956, 2019). "Epitheloid sarcoma cells shed microvesicles high in CD147 that promotes MMP2 expression in recipient fibroblasts." (PMID 32957712, 2020). "CD73 siRNA and CD73 neutralizing antibody were used to confirm that CD73 regulates MMP-2 production in co-cultures of sarcoma cells with fibroblasts." (PMID 31510956, 2019). "Here we show that CD73 expressed on fibroblasts interacts with emmprin and is a required factor for MMP-2 production in co-cultures of sarcoma cells with fibroblasts." (PMID 31510956, 2019). "In this study, we compared MMP secretion patterns by cytokines, PMA, and LPS in two pediatric sarcoma cell lines that express MMP-2 and -9 to different extent." (PMID 24190483, 2014). "In conclusion, our results show that cytokines, inducers and inhibitors regulate MMP-2 and -9 secretion in pediatric sarcoma cell lines, suggesting the clinical value of targeting these proteases for management of sarcomas and their pathogenesis." (PMID 24190483, 2014). "Of interest, a previous study demonstrated significant correlation between NM inhibition of Matrigel invasion and NM modulation of the MMP-2 and -9 activities of the sarcoma cell lines studied." (PMID 24085323, 2013). "Pediatric sarcomas are highly aggressive tumors that are characterized by high levels of matrix metalloproteinase (MMP)-2 and -9 secretions that degrade the ECM and basement membrane, allowing cancer cells to spread to distal organs." (PMID 23900236, 2013). "Adult sarcomas are highly aggressive tumors that are characterized by high levels of matrix metalloproteinase (MMP)-2 and -9 secretions that degrade the ECM and basement membrane, allowing cancer cells to spread to distal organs." (PMID 23661254, 2013). "In this study, we compared MMP secretion patterns by cytokines, PMA and LPS in four adult sarcoma cell lines that express MMP-2 and MMP-9 to different extents." (PMID 24085323, 2013). "Bone was the major contributor of TGF-β and MMP2 whereas both bone and sarcoma cells secreted the chemokine MCP-1 in cocultures." (PMID 19192289, 2009). "Moreover, the expression level of MMP2 in sarcoma was much high than that in normal tissue based on TCGA database." (PMID 29050278, 2017). "The highly aggressive pediatric sarcomas are characterized by high levels of matrix metalloproteinase (MMP)-2 and MMP-9, which play crucial roles in tumor invasion and metastasis by degradation of the extracellular membrane leading to cancer cell spread to distal organs." (PMID 24190483, 2014). "Furthermore, a previous study demonstrated significant correlation between NM inhibition of Matrigel invasion and NM modulation of the MMP-2 and -9 activities of the sarcoma cell lines studied." (PMID 23661254, 2013). "The highly aggressive adult sarcomas are characterized by high levels of matrix metalloproteinase (MMP)-2 and -9, which play crucial roles in tumor invasion and metastasis by degradation of the extracellular membrane leading to cancer cell spread to distal organs." (PMID 24085323, 2013).